AQP4 (aquaporin 4)
Diseases named in the same sentence as AQP4 in open-access papers (continued):
Sharing a sentence is not in itself a finding about the gene and the disease.
astrocytomas (16 papers, 2012 to 2025). "AQP4 over-expression in human astrocytoma was associated with the presence of brain edema detected by the magnetic resonance imaging." (PMID 25886458, 2015). "Furthermore, these cytokines are implicated in the opening of the BBB and are associated with elevated expression of aquaporin-4 (AQP4) in astrocytomas and metastatic adenocarcinomas." (PMID 41361096, 2025). "The expression of AQP4 has been shown to be upregulated in certain forms of astrocytoma, meningioma, and metastatic tumors." (PMID 35847914, 2022). "Processes that affect the migration potential of astrocytes are complex and related to interactions of AQP4 tetramers with the cytoskeleton, as demonstrated in astrocytoma cells." (PMID 33297299, 2020). "AQP4 is upregulated in astrocytomas and metastatic tumors, and the depletion of AQP4 reduces astrocyte cell migration." (PMID 30345080, 2018). "Quantitative Real-time PCR (qRT-PCR) of different graded astrocytomas revealed an upregulation of both isoforms AQP4 M1 and M23 in all astrocytomas investigated." (PMID 27483250, 2016). "A variety of reports suggest that AQP4 is involved in promoting cancer cell migration, and, indeed, AQP4 deletion markedly impaired astrocytoma cell migration and invasion." (PMID 27367682, 2016). "In this work, we furnished proof that the number of OAPs in human astrocytomas decreased from low-grade to high-grade malignancy although the amount of AQP4 protein was increasing." (PMID 27483250, 2016). "For example, AQP1 and AQP4 were massively up-regulated in high-grade astrocytomas, as compared with low-grade ones and normal brain tissues." (PMID 25886458, 2015). "We surmise that as the origin of skin epithelial cells and astrocytes are different, the PKC dependency of AQP4 may be dependent on voltage-dependent channels expressed in astrocytoma and GBM." (PMID 35847914, 2022). "Upregulating AQP4 expression in high-grade astrocytomas may facilitate fluid flow, and the correlation between AQP4 expression and the severity of tumor edema was further confirmed by magnetic resonance imaging." (PMID 36010640, 2022). "A strong correlation between PTBE and upregulated astrocyte AQP4 expression in human astrocytomas and metastatic adenocarcinomas suggests that increased AQP4 expression may be essential to the pathogenesis of PTBE." (PMID 34722268, 2021). "Together with isoform-specific changes in AQP4 localization and redistribution of AQP4 in high-grade astrocytomas, mislocalization of inwardly rectifying K+ channel Kir4.1 was detected in low- and high-grade astrocytomas and oligodendrogliomas." (PMID 33297299, 2020). "AQP5 has been indicated to be also involved in astrocytoma development, although compared to the prominently expressed AQP1 and AQP4, its expression is low." (PMID 36010640, 2022). "In previous studies, polyclonal antibody has been found in cancer patients, such as aquaporin-4 and MOG-IgG in astrocytoma patients." (PMID 36221336, 2022).
bacterial meningitis (16 papers, 2009 to 2024). Inflammation of the membranes surrounding the brain and spinal cord due to a bacterial infection. "This notion is consistent with observations in other experimental models of bacterial meningitis which noted that the loss of AQP4 polarity is accompanied by β-DG degradation." (PMID 36582539, 2022). "Schematic illustration of AQP4 polarity loss being induced by Poldip2 in mouse bacterial meningitis model." (PMID 32790044, 2020). "The mechanism of AQP4 polarity loss being induced by Poldip2 in mouse bacterial meningitis model is summarized in graphical abstract." (PMID 32790044, 2020). "This study aimed to investigate whether Poldip2‐mediated BBB disruption and cerebral edema formation in mouse bacterial meningitis (BM) model occur via induction of AQP4 polarity loss." (PMID 32790044, 2020). "AQP4 gene knocking out can reduce the brain edema of bacterial meningitis, reduce the increase of intracranial pressure and thereby reduce the mortality rate." (PMID 33235702, 2020). "In line with this, there is less edema formation in Aqp4 knockout compared to wild-type mice after bacterial meningitis, focal cerebral ischemia, water intoxication, or spinal cord injury." (PMID 32998402, 2020). "It has also been reported that the expression of AQP4 in brain tissue was significantly up-regulated in bacterial meningitis." (PMID 33235702, 2020). "Three percent sodium chloride (NaCl) treatment has been shown to reduce brain edema and inhibited brain aquaporin 4 (AQP4) expression in bacterial meningitis induced by Escherichia coli." (PMID 23036239, 2012). "Recently, we reported that 3% NaCl inhibited the up-regulation of brain AQP4 protein expression in bacterial meningitis induced by Escherichia coli in rabbits." (PMID 23036239, 2012). "Reduced brain swelling and improved clinical outcome occurred in AQP4−/− mice in a model of bacterial meningitis, demonstrating that altered AQP4 expression may be a maladaptive response that exacerbates periventricular water accumulation." (PMID 24341850, 2014). "Therefore, it could be relevant to include MOG‐IgG and AQP4‐IgG in the diagnostic workup of noncompressive myelitis secondary to bacterial meningitis." (PMID 39222058, 2024). "A study detecting AQP1 and AQP4 in CSF determined that the mean concentration of AQP1 in CSF was significantly higher in patients with bacterial meningitis (BM), AQP4 was also greater but not significantly so." (PMID 23659378, 2013). "We previously reported improved clinical outcome in a mouse model of bacterial meningitis, with greatly reduced meningeal inflammation, though it was not possible to isolate effects of AQP4 on inflammation versus brain water accumulation and intracranial pressure elevation." (PMID 19660138, 2009).
hematoma (16 papers, 2013 to 2026). A hematoma is a collection of blood from a vascular structure into an extravascular space. "Conversely, AQP4 inhibition or knockout produced opposite effects.Melatonin treatment similarly improved AQP4 polarization, glymphatic function,lymphatic drainage, and hematoma resolution, while its effects were blocked bythe receptor antagonist luzindole." (PMID 41504200, 2025). "A recent 2025 study in a collagenase-induced ICH model showed that AQP4 activation enhances glymphatic clearance and promotes hematoma resolution." (PMID 40943104, 2025). "In the prior experiment, AQP4 intervention significantly affected hematoma clearance and neurological function scores in murine brain slices." (PMID 39530196, 2025). "Upregulation of AQP4 improves glymphatic system function, thereby facilitating hematoma clearance, and reducing BBB permeability, neuronal death rates, and iron deposition." (PMID 39530196, 2025). "The glymphatic system, facilitated by AQP4, plays a crucial role in hematoma clearance following cerebral hemorrhage." (PMID 39530196, 2025). "AQP4 activation improved glymphatic system function, leading to a wider distribution, improved neurological function, and reduced hematoma." (PMID 39530196, 2025). "In the ICH model using the AQP4 inhibitor and Aqp4−/− mice, reduced AQP4 expression resulted in an amplified hematoma area and volume, exacerbated neurological deficits, and impeded hematoma clearance." (PMID 39530196, 2025). "MFP administration upregulated AQP4 expression, enhanced glymphatic system function, and facilitated hematoma clearance." (PMID 39530196, 2025). "Upregulation of AQP4 improves glymphatic system function, facilitates hematoma clearance, and promotes brain tissue recovery." (PMID 39530196, 2025). "In an optimized hematoma expansion model, AQP4 knock-out resulted in an increased hematoma volume and increased severity of BBB breakdown, which indicates that AQP4 plays a role in attenuating hematoma expansion and maintenance of BBB integrity." (PMID 37304071, 2023). "A recent study has shown that AQP4 knockout mice have larger hematoma areas and more severe damage to the BBB in a novel model of hematoma expansion." (PMID 35111362, 2022). "In this work, focal brain cooling reduced both AQP4 expression and concentration following a stereotactic injection of thrombin, simulating deep intracerebral hematoma in rat." (PMID 30333785, 2018). "Compared to AQP4+/+ mice, AQP4 deletion significantly decreased specific gravity of brain tissue surrounding hematoma at the three time points after ICH (p<0.05)." (PMID 23805198, 2013). "Furthermore, Wenchao Chen demonstrated that mifepristone upregulated AQP4 expression to promote its perivascular polarization profile to improve GS function to promote post‐ICH hematoma clearance." (PMID 41578884, 2026). "Conversely, the TNG‐020 intervention and Aqp4−/− groups demonstrated larger hematoma areas." (PMID 39530196, 2025). "In our study, both pharmacological inhibition and genetic knockout of AQP4 reduced the distribution of tracers and contrast agents, while treatment with an AQP4 agonist increased their distribution, ultimately influencing hematoma clearance and neurological outcomes." (PMID 39530196, 2025). "However, we also observed that over time, the hematoma in the AQP4 knockout or inhibition groups gradually decreased, and the difference from other groups diminished." (PMID 39530196, 2025). "Therefore, this study aims to explore the role of AQP4 and the glymphatic system in hematoma clearance after ICH, providing new insights into post‐ICH recovery." (PMID 39530196, 2025). "At 7 days post‐ICH, a consistent pattern emerged: compared to the ICH group, the ICH + MFP group exhibited a reduced hematoma volume (p < 0.0001), whereas both the Aqp4−/− (p = 0.0032) and TGN‐020 (p = 0.0002) groups demonstrated an increase in hematoma volume." (PMID 39530196, 2025).
hematoma (continued). "In the central nervous system, aquaporin-4 plays a critical role in increasing membrane permeability to water, which expressed in the outer membrane, especially in areas typically invaded by inflammatory cells, leads to hematoma formation and expansion." (PMID 39076594, 2024). "Aquaporin-4 on the CSDH outer membrane may cause excessive fluids into subdural space and contribute to hematoma development." (PMID 26495025, 2015). "We believe that the elevation of AQP4 enhances CSF‐ISF exchange, improves fluid drainage, increases overall fluid transport, and reduces edema formation, thereby accelerating hematoma clearance." (PMID 39530196, 2025).
autoimmune disease of the central nervous system (15 papers, 2015 to 2025). "Neuromyelitis optica (NMO) is an autoimmune disease of the central nervous system (CNS) that is mediated by autoantibodies against the water-channel protein AQP4." (PMID 38383779, 2024). "Neuromyelitis optica (NMO) and NMO spectrum disorders are central nervous system autoimmune diseases mediated by aquaporin 4 antibodies (AQP4-IgG) that can simultaneously or sequentially affect the optic nerve and spinal cord." (PMID 39654895, 2024). "Neuromyelitis optica (NMO) is an autoimmune disorder of the central nervous system (CNS) mediated by antibodies to the water channel protein AQP4 expressed in astrocytes." (PMID 28058717, 2017). "Neuromyelitis optica (NMO) is an autoimmune disorder of the central nervous system, which is characterized by autoantibodies directed against the water channel aquaporin-4 (AQP4)." (PMID 25986484, 2015). "Serological markers of Nuromyelitis Optica (NMO), an autoimmune disorder of the central nervous system, are autoantibodies targeting the astrocytic water channel aquaporin-4 (AQP4)." (PMID 26599905, 2015). "Neuromyelitis optica (NMO), an autoimmune disease of the central nervous system, is characterized by an autoantibody called NMO-IgG that recognizes the extracellular domains (ECDs) of aquaporin-4 (AQP4)." (PMID 28955892, 2016).
Encephalopathy (14 papers, 2013 to 2025). Encephalopathy is a term that means brain disease, damage, or malfunction. "In addition, the induction of AQP4 expression and edema formation has been well studied in animals with influenza-associated encephalopathy induced by proinflammatory cytokines, including IL-1, IL-6 and TNF-α in cultured astrocytes." (PMID 29216295, 2017). "Childhood-onset ADEM requires a polyfocal demyelinating clinical manifestation with encephalopathy; the presence of AQP4-IgG favors the diagnosis of NMOSD." (PMID 35585974, 2022). "NMO patients with EBLs had higher rates of encephalopathy symptoms (37.5% vs. 5.6%, p = 0.004), homonymous hemianopia (18.8% vs. 0%, p = 0.011) and AQP4 seropositivity (100% vs. 69.8%, p = 0.008) than NMO patients without EBLs (NEBLs)." (PMID 23819854, 2013). "Additionally, studies investigating endotoxemia-induced encephalopathy have identified increased AQP4 expression in the hippocampus, suggesting its involvement in the pathogenesis of cognitive dysfunction." (PMID 39544938, 2024). "The loss of AQP4 polarity is considered to lead to Ca2+ overload and inhibits PPAR-γ/mTOR-dependent autophagy in astrocytes, which subsequently activates astrocytes and impairs BBB-glymphatic function in sepsis-associated encephalopathy." (PMID 38976012, 2024). "Hence, IPND 2015 proposes that children who present with polyfocal demyelinating lesions with encephalopathy and have seropositivity for AQP4-IgG, should have a diagnosis of NMOSD over ADEM." (PMID 31163654, 2019). "Moreover, about 45% of children who are seropositive for AQP4-IgG, experience recurrent cerebral manifestations including encephalopathy." (PMID 31163654, 2019). "Overall, we recruited 58 subjects seropositive for MOG-IgG and seronegative for AQP4-IgG, including 23 (39.7%, 23/58) subjects with seizures and/or encephalopathy and 35 subjects without seizures or encephalopathy." (PMID 31080435, 2019).
gastric cancer (14 papers, 2011 to 2025). A primary or metastatic malignant neoplasm involving the stomach. "Xu and colleagues found a subsequent loss of AQP4 during carcinogenesis in gastric cancer and suggested AQP4 as a marker for normal proliferating gastric cells." (PMID 36233821, 2022). "A subsequent loss of AQP4 during carcinogenesis is also described in gastric cancer and AQP4 was therefore suggested to be used as a marker for normal proliferating gastric cells." (PMID 21548930, 2011). "We found that miR-3613-5p promotes the progression of CAG to gastric cancer by inhibiting the expression of AQP4." (PMID 40255569, 2025). "For example, LINC00629 upregulates AQP4 expression by binding to miR-196b-5p, suppressing gastric cancer cell proliferation and migration." (PMID 40255569, 2025). "Our findings further suggest that miR-3613-5p negatively regulates AQP4, exacerbating gastric mucosal inflammation and intestinal metaplasia, thus accelerating gastric cancer cell proliferation and migration." (PMID 40255569, 2025). "LINC00629 was reported to suppress tumor progression by upregulating AQP4 and competitively binding to miR-196b-5p in gastric cancer." (PMID 37528150, 2023). "Another study reported that LINC00629 suppressed tumour progression by upregulating AQP4 and competitively binding to miR-196b-5p in gastric cancer." (PMID 36539799, 2022). "Consistently, the prognostic correlation of AQP4 mRNA expression in gastric cancer showed significant poor prognosis in all gastric cancer patients primarily in stage III, as well as in male intestinal gastric cancer patients." (PMID 29678898, 2018). "We reported for the first time that AQP4 protein and mRNA expression levels in gastric cancer tissue were significantly lower than those in normal gastric tissue." (PMID 21943213, 2011). "This implies that AQP4 may serve a protective role in gastric cancer development, highlighting its potential as a therapeutic target." (PMID 40255569, 2025). "Recent studies suggest that AQP4 downregulation may facilitate gastric cancer progression by promoting an inflammatory microenvironment conducive to tumor growth." (PMID 40255569, 2025). "In gastric cancer, AQP4 expression is typically decreased compared to normal gastric mucosa." (PMID 40255569, 2025). "Interestingly, we detected a downregulation of AQP4, which, when overexpressed, reduce gastric cancer cells proliferation." (PMID 34012923, 2021). "Indeed, AQP4 protein and mRNA expression levels in gastric cancer tissue were significantly lowered than those in normal gastric tissue." (PMID 34721627, 2021). "In which, we revealed AQP3, AQP9, and AQP11 mRNA expression were associated with improved OS in all gastric cancer patients especially with intestinal subtypes, whereas AQP0, AQP1, AQP4, AQP5, AQP6/2L AQP8, and AQP10 mRNA expression were associated with poor OS in all gastric cancer patients." (PMID 29678898, 2018). "Interestingly, IHC analysis through HPA database also demonstrated significant AQP4 protein expression in normal tissues compared with adjacent gastric cancer tissue." (PMID 29678898, 2018). "miR-3613-5p inhibits the expression of the AQP4 gene by binding to its 3′UTR, thereby promoting the progression from CAG to gastric cancer." (PMID 40255569, 2025). "In gastric cancer, LINC00629 was found to suppress tumor progression by upregulating AQP4 and competitively binding to miR-196b-5p." (PMID 36445338, 2022). "By inhibiting AQP4 expression, miR-3613-5p promotes the progression from CAG to gastric cancer." (PMID 40255569, 2025). "AQP4 and AQP6/2L mRNA overexpression were correlated with poor OS in stage III gastric cancer." (PMID 29678898, 2018). "Alternatively, we found an elevated expression AQP4 protein trend toward normal gastric tissues, while no expression was detected in gastric cancer tissues." (PMID 29678898, 2018).
gastric cancer (continued). "In the present study, we documented that high mRNA level of AQP0, AQP4, AQP2L/6, and AQP8 were associated with worse OS in either HER2 positive or HER2 negative gastric cancer patients." (PMID 29678898, 2018).